SPIB (Spi-B transcription factor)
Diseases named in the same sentence as SPIB in open-access papers (continued):
Sharing a sentence is not in itself a finding about the gene and the disease.
SPIB also shares sentences with these, for which no sentence is quoted: hepatocellular carcinoma (5 papers); gastric cancer (2); liver cancer (2); adenocarcinoma (1); Allergy (1); Autoimmunity (1); B-cell acute lymphoblastic leukemia (1); blastic plasmacytoid dendritic cell neoplasms (1); brain tumor (1); cervical cancer (1); CNS lymphomas (1); digestive system disorder (1); emphysema (1); food allergies (1); head and neck cancer (1); head and neck squamous cell carcinoma (1); heart failure (1); helminth infection (1); hematological diseases (1); latent infection (1); lung (1); malnutrition (1); memory impairment (1); multiple sclerosis (1); non-Hodgkin lymphoma (1); non-small cell lung carcinoma (1); primary biliary cholangitis (1); prostate carcinoma (1); psoriatic arthritis (1); Salmonella Infections (1).
A further 2 diseases each share a sentence with SPIB in 1 paper.